ATP7B (ATPase copper transporting beta)
Diseases named in the same sentence as ATP7B in open-access papers (continued):
Sharing a sentence is not in itself a finding about the gene and the disease.
Wilson disease (continued). "Wilson's disease (WD) is an inherited autosomal recessive disorder caused by mutations in the ATP7B gene that encodes for a P‐type ATPase protein involved in copper transport and excretion." (PMID 32202078, 2020). "Wilson disease is a rare autosomal recessive genetic disorder linked to a mutation of the copper-transporting P-type ATPase (ATP7B) gene, encoding the ATP7B protein, the main regulator of the hepatic metabolism of copper in the body." (PMID 33208122, 2020). "The importance of MBD5-6 in copper transfer is also linked to Wilson’s disease, wherein most of the mutations in the N-terminus domain of ATP7B were reported in this unit." (PMID 32748830, 2020). "Wilson’s disease (WD) is an autosomal recessive disorder of copper metabolism caused by defects in the ATPase gene (ATP7B)." (PMID 31547461, 2019). "Wilson’s disease (WD), known as progressive hepatolenticular degeneration, is a genetic disorder commonly supposed due to a mutation of gene ATP7B responsible for copper metabolism, and usually occurs in children." (PMID 30804230, 2019). "Disruption of ATP7B expression, activity and/or apical delivery causes Wilson disease with a strong buildup of Cu and subsequent hepatocyte damage, culminating in liver failure." (PMID 31540259, 2019). "Recently, it has been shown that the disruption of an MTF1 binding site by a homozygous variant in the promoter of Atp7b likely causes Wilson disease." (PMID 31491970, 2019). "Wilson disease (WD) is an autosomal recessive disease caused by mutations in ATP7B encoding a copper transporter." (PMID 30709419, 2019). "Wilson disease is caused by a genetic mutation of the ATP-dependent copper transporter protein ATP7B and it is characterized by hepatic copper accumulation and hepatitis." (PMID 31614590, 2019). "This method was applied to convert urine-derived cells from both healthy donors and patients with Wilson’s disease (WD), a genetic disorder caused by mutations in the ATP7B gene." (PMID 31071994, 2019). "Mutations in genes encoding ATP7A and ATP7B cause two genetic disorders of Cu homeostasis, Menkes disease and Wilson disease, respectively." (PMID 31540259, 2019). "Wilson disease is characterized by loss-of-function mutations in a P-type copper ATPase, ATP7B, which is expressed mostly in liver." (PMID 29362485, 2018). "The H1069Q substitution is the most frequent mutation of the Cu transporter ATP7B that causes Wilson disease in the Caucasian population." (PMID 29954118, 2018). "Several studies have shown that APOE ε4-positive genotype is associated with earlier symptomatic visibility of Wilson’s disease, particularly amongst patients harboring the ATP7B p.H1069Q homozygous patients in women." (PMID 30126847, 2018). "The model was then used to investigate Wilson disease with various degrees of loss of ATP7b enzyme activity." (PMID 29354285, 2018). "Recently, polymorphisms in the ATP7B gene, which is responsible for Wilson disease and a part of IEM-disease group 14, have been associated with increased risk of AD." (PMID 29404805, 2018). "Mutations in the ATP7B gene were identified as the cause of Wilson disease in 1993 and this gene is still the only one associated with the disorder." (PMID 29914392, 2018). "ATP7B is a target of several hundred mutations that lead to Wilson disease, a chronic copper toxicosis." (PMID 29330485, 2018). "The second mammalian Cu-transporting P-type ATPase gene, Atp7b, is mutated in the Cu overload associated with Wilson disease." (PMID 29333545, 2018). "H1069Q substitution represents the most frequent mutation of the copper transporter ATP7B causing Wilson disease in Caucasian population." (PMID 29674751, 2018). "The identification of mutations in the ATP7B gene is the one of the useful diagnostic tools for diagnosis and treatment orientation for patients with Wilson disease." (PMID 29914392, 2018).
Wilson disease (continued). "The H1069Q mutation in European populations and the R778L mutation in Asian populations are the most common ATP7B mutation observed in patients with Wilson’s disease." (PMID 30126847, 2018). "Mutations in the ATP7B gene leads to Wilson’s disease (WD), an inherited autosomal recessive disorder of copper dyshomeostasis, characterized by excessive hepatic copper accumulation and decreased serum ceruloplasmin levels." (PMID 30469339, 2018). "Both of these key functions in copper metabolism are mediated by the copper-transporting P-type ATPase; ATP7b.28,29 Mutations in the gene encoding ATP7b can result in the accumulation of copper deposits in the body leading to Wilson disease." (PMID 29354285, 2018). "Wilson disease is typically caused by homozygous or compound heterozygous mutations in the ATP7B gene." (PMID 29914392, 2018). "Information about mutations in the ATP7B gene will be helpful for efficiently diagnosing Wilson disease and providing early therapeutic intervention for patients." (PMID 29914392, 2018). "Wilson disease (WD) is a rare autosomal recessive genetic disorder caused by mutations in the ATP7B gene located on chromosome 13." (PMID 29621974, 2018). "Hepatolenticular degeneration, also termed as Wilson’s disease is an autosomal recessive genetic disorder and is characterized by ATP7B gene mutations, leading to defective copper metabolism." (PMID 30126847, 2018). "Wilson’s disease (WD) is a rare autosomal recessive metabolic disease caused by ATP7B gene mutations tat cause excessively high copper levels, particularly in the liver and brain." (PMID 30097039, 2018). "Wilson’s disease (WD) is a rare autosomal recessive disease, in Europe mostly caused by mutations in the ATP7B gene which encodes a copper regulating protein leading to a defect in biliary copper excretion." (PMID 30241550, 2018). "Mutations that impair transport activity or disrupt intracellular targeting of ATP7B cause Wilson disease, chronic copper toxicosis that primarily affects the liver and the brain." (PMID 29330485, 2018). "Mutations in ATP7B gene cause Wilson’s disease, a genetic disease inherited by 1 in 30,000 to 100,000 people." (PMID 30344245, 2018). "Wilson disease is an autosomal recessive genetic disorder caused by loss-of-function mutations in the P-type copper ATPase, ATP7B, which leads to toxic accumulation of copper mainly in the liver and brain." (PMID 29362485, 2018). "Mutations in ATB7A and ATP7B are not only responsible for Menkes and Wilson diseases, but can also be involved in other disorders, such as distal motor neuropathy and Alzheimer’s disease." (PMID 28684721, 2017). "Recently two missense mutations in copper transporters ATP7B (Wilson disease gene) and ATP7A (Menkes disease gene) that were respectively positively and negatively associated to hepatic copper levels were identified in Labrador retrievers." (PMID 28459846, 2017). "The Cu-transporting ATPase encoded by CCC2 is the yeast ortholog of human ATP7A and ATP7B, mutations in which cause Cu homeostasis defects linked to Menkes’ and Wilson's diseases, respectively." (PMID 28867595, 2017). "The gene correction on iPSCs can be applied for patients with monogenic inherited metabolic liver diseases, like Alpha-1 antitrypsin deficiency and Wilson’s disease (mutation in ATP7B gene)." (PMID 28670513, 2017). "Mutation in the copper transporter ATP7B gene causes Wilson disease, an autosomal recessive condition with an estimated wide prevalence of 1–9 in 100,000." (PMID 28684721, 2017). "Wilson’s disease (WD) is a rare autosomal recessive inherited disease, involving mutation of the ATP7B gene on chromosome 13, which induces an adenosine triphosphate (ATP) production deficiency." (PMID 28384152, 2017). "Our findings imply that reduced stability and enhanced dynamics of MBD1 or MBD6 is the origin of ATP7B dysfunction in Wilson disease patients with the G85V or G591D mutation." (PMID 27744583, 2017).
Wilson disease (continued). "These analyses yielded one parental pair (among 285 total) as carriers for variants in ATP7B, associated with Wilson disease (MIM:277900)." (PMID 28554332, 2017). "Wilson’s disease (WD) is an autosomal recessive disorder caused by mutations in the ATP7B gene leading to excessive copper overload, predominantly in the liver and the brain." (PMID 28732478, 2017). "Mutations in ATP7B constitute the basis of Wilson disease, a genetic disorder where Cu accumulates in tissues, often resulting in neurological or psychiatric symptoms together with liver dysfunction." (PMID 27744583, 2017). "Defects in the ATP7B gene encoding a copper transporting Cu-ATPase disrupt the homeostatic copper balance leading to Wilson disease (WD), that is characterized by reduced biliary Cu excretion, and impaired Cu incorporation into Cp." (PMID 28197071, 2017). "In Wilson Diseases caused by a mutation in ATP7B gene, a Golgi copper transporter, Cp is produced in the apo-form that is secreted in the blood stream where it is rapidly degraded." (PMID 28118841, 2017). "In another study, researchers tried to generate iPSCs from a Chinese patient with Wilson’s disease (WD) that bears the R778L Chinese hotspot mutation in the ATPase Cu2+ transporting beta polypeptide (ATP7B) gene." (PMID 28670513, 2017). "Wilson disease (WD) is an autosomal recessive disorder of copper metabolism (OMIM #277900) caused by allelic variants in ATP7B gene (OMIM # 606882)." (PMID 28717664, 2017). "The Variation service can be used to retrieve all entries with Wilson disease associated variants from the set of human genetic variants; which results in a single entry human Copper-transporting ATPase 2, ATP7B gene, (P35670)." (PMID 28383659, 2017). "Wilson disease (WD) is an autosomal recessive disorder of copper metabolism caused by allelic variants in ATP7B gene." (PMID 28717664, 2017). "Mis-folding and aberrant retention in the ER have been previously reported in Wilson disease-associated ATP7B mutations." (PMID 26747866, 2016). "Mutations in ATP7B lead to Wilson disease, which is characterized by a predominantly hepatic copper accumulation." (PMID 26747866, 2016). "We show, for the first time, that Labrador retrievers and humans with Wilson disease share ATP7B as the causal gene." (PMID 26747866, 2016). "Mutations in the copper transporter ATP7B result in the copper overload disorder Wilson disease (WD)." (PMID 26861285, 2016). "In humans, the extent of damage associated with elevated copper is exemplified by liver failure and neurodegeneration in patients with Wilson’s disease, a genetic disorder caused by mutations in a copper transporting ATPase ATP7B and copper overload." (PMID 27472369, 2016). "Wilson’s disease (WD) is an autosomal recessive disorder caused by mutations in the ATP7B resulting in copper overload in the liver and brain." (PMID 27992490, 2016). "The toxic milk mouse (tx), a well-characterised model for Wilson's disease, has an autosomal recessive mutation in the Atp7b gene (A4066G/Met1356Val) that causes substantial changes to systemic copper distribution." (PMID 27175597, 2016). "Wilson disease results from mutations in ATP7B and is associated with copper accumulation in the liver and secondarily in the brain, resulting in hepatic cirrhosis and neuronal degeneration." (PMID 26747866, 2016). "The association between ATP7B gene (ATPase, Cu++ transporting, beta polypeptide) and Wilson’s disease (C0019202, Wilson’s Disease or Hepatolenticular Degeneration) is the one achieving the highest score in DisGeNET." (PMID 25877637, 2015). "ATP7B is the Wilson’s disease gene, and patients with both alleles mutated have accumulation of large amounts of copper, and copper toxicity." (PMID 26633489, 2015). "Such copper status develops as a result of the low activity of the Atp7b gene (during the ETCM) or Atp7b mutations (Wilson disease)." (PMID 26474410, 2015).
Wilson disease (continued). "Wilson’s disease (WD) is an autosomal recessive genetic disorder, and is caused by disabling mutations in both copies of the ATP7B gene." (PMID 24748564, 2014). "In our view, this sequence of events outlines the main mechanism, which is utilized by hepatocytes to remove excess Cu from liver and which is affected by ATP7B mutations in Wilson disease." (PMID 24909901, 2014). "Wilson’s disease is an autosomal recessive disorder caused by more than 500 mutations in ATP7B gene presenting considerably clinical manifestations heterogeneity even in patients with a particular mutation." (PMID 24897373, 2014). "Copper accumulation in tissues due to a biallelic pathogenic mutation of the gene: ATP7B results in a clinical phenotype known as Wilson disease (WD)." (PMID 24368744, 2014). "Wilson’s disease (WD), a rare cause of neuropsychiatric deterioration, is associated with mutations in the ATP7B gene." (PMID 24555712, 2014). "Wilson's disease (WD), also known as hepatolenticular degeneration, is an autosomal recessive inherited disease that is caused by a mutation in the ATP7B gene and is characterized by impaired biliary copper excretion and lack of ceruloplasmin synthesis." (PMID 25375371, 2014). "On the other extreme, Wilson's disease results from the mutation of a different transporter protein, ATP7B, which is involved in the transport of copper into the bile and ultimately in copper excretion." (PMID 24672633, 2014). "Wilson's disease is a rare autosomal recessive genetic disorder of copper metabolism characterized by numerous mutations in the ATP7B gene on chromosome 13." (PMID 25276143, 2014). "Activation of lysosomal exocytosis stimulates both the delivery of ATP7B and its Wilson-disease-causing mutant to the canalicular membrane domains of hepatocytes and the release of excess Cu into the bile." (PMID 24909901, 2014). "Wilson disease (WD), an orphan disease, is caused by mutations in the ATP7B gene on chromosome 13 leading to an imbalance in copper homeostasis." (PMID 24892424, 2014). "Conversely, copper overload in the Atp7b−/− mouse model of Wilson disease is associated also with reduced brain and hepatic concentrations of cholesterol, lathosterol, desmosterol, 8-hydrocholesterol, and 7-dehydrocholesterol." (PMID 23720634, 2013). "Proper counseling of patients with Wilson disease, and their families necessitates finding mutation in ATP7B gene." (PMID 24003324, 2013). "Wilson's disease, a genetic disorder of copper metabolism, is caused by mutations in the ATP7B gene." (PMID 23843956, 2013). "ATP7A- and ATP7B-deficiency, due to genetic mutation, underlie the inherited copper transport disorders, Menkes and Wilson diseases, respectively." (PMID 23986700, 2013). "An ApoE-copper connection was further supported by the finding that in Wilson disease patients with the common H1069Q mutation in the copper transporter ATP7B, an earlier onset of symptoms is associated with the APOE-ε4 genotype." (PMID 23720634, 2013). "Wilson's disease (WD) is an autosomal recessive inherited disorder caused by mutations in the ATPase Cu2+ transporting beta polypeptide gene (ATP7B)." (PMID 23843956, 2013). "The loss of ATP7B function causes Wilson’s disease, while mutations that eliminate or reduce the activity of ATP7A cause MD." (PMID 22992316, 2012). "Wilson disease (WD) is an autosomal recessive disease arising from a mutation in the ATP7B gene, which results in the failure of hepatocytes to excrete copper into bile, leading to the hepatic copper accumulation and cell injury." (PMID 22629446, 2012). "Wilson disease (WD) is characterized by the accumulation of copper arising from a mutation in the ATP7B gene." (PMID 22629446, 2012). "Before interpreting the structure/function relationships of Wilson disease mutations and studying Mg2+-ATP binding, the first step has been the generation and experimental validation of the 3D models for ATP7B." (PMID 22046264, 2011).
Wilson disease (continued). "Mutations in the gene ATP7B cause Wilson disease, a copper storage disorder with a high phenotypic and genetic heterogeneity." (PMID 20082719, 2010). "Wilson's disease (WD) is an autosomal recessive inherited copper metabolism disorder caused by mutation of the ATP7B gene 2,3." (PMID 20556197, 2009). "Wilson disease (WD), an autosomal recessive disorder caused by pathogenic variants in the ATP7B gene, is characterized by abnormal copper accumulation in the liver, brain, and other organs, leading to hepatic dysfunction, neurological manifestations, and multisystemic complications." (PMID 41523988, 2026). "Wilson’s disease is an autosomal recessive disorder of copper metabolism first defined in 1912 that causes dysfunction of the intracellular copper transporter ATP7B and subsequent excessive copper accumulation in multiple organ systems, primarily the liver, eyes, and brain." (PMID 41552187, 2025). "Wilson’s disease (WD) is an autosomal recessive ailment caused by ATP7B gene mutations." (PMID 40002122, 2025). "Hepatolenticular degeneration is an autosomal recessive disease with ATP7B as the pathogenic gene." (PMID 40557282, 2025). "In ATP7B variants, there might be an increase in exchangeable Cu pool due to the lack of excess Cu export to the bile from the liver as seen in Wilson disease." (PMID 40847318, 2025). "Two dogs were homozygous for the variant associated with Wilson disease (ATP7B gene)." (PMID 40151526, 2025). "We also detected one case each (2.5% of total abnormalities) of Wilson’s disease (mutations in ATP7B), cystic fibrosis (mutations in CFTR), Cockayne syndrome (mutations in ERCC6), auditory neuropathy (mutations in OTOF), and autosomal recessive polycystic kidney disease (mutations in PKHD1)." (PMID 41329681, 2025). "In fact, decreased CP plasma levels due to impairment of CP copper loading is eminently demonstrated in Wilson disease, where variants in the copper loading transporter ATP7b result in the expression of an incorrectly folded CP and its rapid degradation (e.g., see70)." (PMID 40043514, 2025). "Additionally, one Deerhound and one French Bulldog were homozygous for the ATP7B variant linked to Wilson disease." (PMID 40151526, 2025). "Wilson disease arises from inherited ATP7B mutations while CAH in dogs might be more influenced by excess dietary copper with ATP7B mutations playing a lesser role." (PMID 41427142, 2025). "In addition, ATP7B variants—causative in Wilson’s disease (WD)—have been linked to disrupted copper metabolism and increased AD risk." (PMID 41008575, 2025). "The most common KSD-associated VUS were sucrase-isomaltase deficiency (SI, N = 8), Wilson disease (ATP7B, N = 7), pseudoxanthoma elasticum and generalized arterial calcification of infancy (ABCC6, N = 5), CYP24A1-related hypercalcemia (CYP24A1, N = 4), and hypouricemia Renal 1 (SLC22A12, N = 4)." (PMID 40126616, 2025). "Wilson’s disease (WD) is a rare autosomal recessive genetic disorder of copper metabolism caused by pathogenic mutations in the ATP7B gene located on chromosome 13, which encodes a copper-transporting P-type ATPase (ATP7B)." (PMID 40616145, 2025). "This is similar to Wilson disease where there is a loss of function of ceruloplasmin and ATP7B." (PMID 40847318, 2025). "Our study suggests that individuals with Wilson’s disease or ATP7B-defective alleles who also harbor NAT2 UAs may be at increased risk of INH-induced hepatotoxicity." (PMID 38424191, 2024). "Wilson disease (excess copper) is caused by different mutations of the ATP7B gene." (PMID 38305803, 2024). "ATOX1 transfers Cu+ to membrane-bound Cu(I) exporters, the Cu-ATPases ATP7A and ATP7B, also known as the Menkes disease protein and Wilson’s disease protein, respectively, due to their deficiencies eliciting the respective pathobiochemical alterations in humans." (PMID 38727263, 2024).